TAAR1 (trace amine associated receptor 1)
Diseases named in the same sentence as TAAR1 in open-access papers (continued):
Sharing a sentence is not in itself a finding about the gene and the disease.
Cognitive impairment (6 papers, 2017 to 2023). Abnormal cognition is characterized by deficits in thinking, reasoning, or remembering. "As mentioned, TAAR1 agonism can attenuate chronic stress-induced cognitive impairments possibly by restoring excitatory/inhibitory imbalance and structural alterations in the mPFC." (PMID 34947997, 2021). "Taken together, our data indicate that TAAR1 agonism may provide a novel therapeutic approach in the treatments of disorders involving Aβ-induced cognitive impairments, such as AD." (PMID 35887159, 2022). "Interestingly, specific deletion of TAAR1 in the mPFC mimicked some of the cognitive deficits induced by chronic stress." (PMID 34947997, 2021). "In addition, TAAR1 agonists are able to suppress the hyperlocomotion induced by the NMDA antagonist, decrease impulsive behavior in mice and reverse the cognitive impairments in rats treated with the glutamate NMDA receptor antagonist." (PMID 31130864, 2019). "TAAR1 agonists are proposed to potentially possess efficacy across a wider spectrum of symptom domains than the current antipsychotics acting as D2R antagonists, including negative symptoms and cognitive impairment, while exhibiting a reduced propensity for side-effects." (PMID 38634067, 2023).
metabolic syndrome (6 papers, 2021 to 2025). A cluster of metabolic risk factors for CARDIOVASCULAR DISEASES and TYPE 2 DIABETES MELLITUS. "For instance, accumulating data demonstrate the positive effect of TAAR1 agonists on the dynamics of metabolic syndrome progression and MetS-associated disease development." (PMID 38002300, 2023). "Assuming that TAAR1 is the prospective therapeutic target for diseases associated with monoamine signaling disorders, we believe that TA signaling pathways should be kept in mind when developing new pharmaceutical approaches to managing metabolic syndrome." (PMID 38002300, 2023). "Our findings demonstrating tryptamine/phenethylamine-mediated TAAR1 signaling pathway as the key molecular axis underlying R. gnavus-induced insulin resistance is of utmost importance and explained the molecular mechanisms of increased prevalence of metabolic syndrome in IBS." (PMID 37591886, 2023). "In individuals with metabolic syndrome, TAAR1 expression and its functional interactions appear to be dysregulated, suggesting its involvement in metabolic dysfunction." (PMID 41155326, 2025).
migraine (4 papers, 2016 to 2025). "Insight into TAAR1 signaling in sensory neurons provides attractive targets for the treatment of headache disorders such as migraine." (PMID 37158881, 2023). "In a mouse model of migraine induced by electrical stimulation of the dura mater surrounding the superior sagittal sinus, blockade of TAAR1 signaling attenuated mechanical allodynia; this effect was occluded by lentiviral overexpression of Kv1.4 in TG neurons." (PMID 37158881, 2023). "Collectively, these findings suggested that Kv1.4 participated in TAAR1-mediated pain sensitivity in an ES model of migraine." (PMID 37158881, 2023). "Next, we examined the possible role of TAAR1 signaling in a mouse model of migraine." (PMID 37158881, 2023).
narcolepsy (4 papers, 2017 to 2025). A sleep disorder characterized by a tendency for excessive sleepiness during the day which occurs even after adequate sleep in the nighttime. "Although these represent promising results, future clinical trials are required to determine the utility of TAAR1 agonists in the treatment of narcolepsy." (PMID 33879769, 2021). "Previously, we reported that TAAR1 partial agonists promote wakefulness in rodents and reduces cataplexy in two mouse models of narcolepsy, suggesting promise for treatment of this sleep disorder." (PMID 29456505, 2018). "Interestingly, TAAR1 agonists reduced cataplexy in two mouse models of narcolepsy, a sleep disorder characterized by excessive sleepiness and REM sleep abnormalities." (PMID 33879769, 2021). "Both full and partial TAAR1 agonists also suppress REM sleep and alleviate cataplexy in mouse models of narcolepsy, suggesting utility for TAAR1-directed compounds in treating sleep disorders." (PMID 29456505, 2018).
bipolar disorder (3 papers, 2017 to 2025). A disorder of the brain that causes unusual shifts in mood, energy, activity levels and the ability to carry out day-to-day tasks. "Beyond the genetic factors, animal studies have provided compelling evidence for the involvement of TAAR1 in the pathophysiology of bipolar disorder." (PMID 40351432, 2025). "Although these findings are intriguing, our understanding of TAAR1 and its specific role in bipolar disorder remains largely unclear." (PMID 40351432, 2025). "Since the effects of TAAR1 agonists on bipolar disorder may arise from biased regulation of GSK3β pathways, it would be insightful to investigate whether biased TAAR1 agonists could yield different behavioral outcomes in subsequent studies." (PMID 40351432, 2025). "A family-based association study pointed towards a potential involvement of the TAAR6 locus in the development of bipolar disorder, while the loci for TAAR1 and TAAR5 showed no significant associated risk." (PMID 40351432, 2025). "Given the role of TAAR1 in GSK3β regulation, it is reasonable to hypothesize that TAAR1 agonists may influence the progression of bipolar disorder by modulating GSK3β signaling pathways." (PMID 40351432, 2025). "In an animal model of bipolar disorder induced by ouabain, PCC0105004, a novel TAAR1 agonist, was shown to produce potential antimanic-like and antidepressant-like efficacy in mice." (PMID 40351432, 2025).
cocaine addiction (3 papers, 2015 to 2018). "Intriguingly, both partial and full TAAR1 activation exhibit desirable behavioural effects in animal models of cocaine addiction." (PMID 29066851, 2017). "More recent studies have focused on examining the therapeutic-like effects of TAAR1 agonists on cocaine addiction." (PMID 25762894, 2015). "On the basis of these data, and considering that TAAR1 agonists have been shown to have clear therapeutic-like effects in models of cocaine addiction, it may be tempting to speculate that such potential clinical application could be expanded to METH addiction." (PMID 25762894, 2015). "Moreover, the two partial agonists, RO5203648 and RO5263397 were able to block cocaine relapse, further supporting the development of TAAR1-based pharmacotherapies in cocaine addiction." (PMID 25762894, 2015).
fibromyalgia (3 papers, 2016 to 2024). A chronic disorder of unknown etiology characterized by pain, stiffness, and tenderness in the muscles of neck, shoulders, back, hips, arms, and legs. "While this is merely theoretical at this time, polymorphism of TAAR1 has been linked to fibromyalgia sensitivity, and fibromyalgia may involve an immune system component." (PMID 30013475, 2018). "TAAR1 gene polymorphism may be interlinked to the risk of developing fibromyalgia." (PMID 38672247, 2024).
Insulin resistance (3 papers, 2020 to 2023). Increased resistance towards insulin, that is, diminished effectiveness of insulin in reducing blood glucose levels. "In the OGTT and ITT studies, treatment with EPPTB, a specific TAAR1 antagonist, significantly reduced tryptamine and phenethylamine-induced glucose intolerance and insulin resistance in mice (p < 0.05 in all cases)." (PMID 37591886, 2023). "We then investigated the pharmacological antagonism of TAAR1 on glucose tolerance and insulin resistance in antibiotics-treated mice induced by gut dysbiosis including R. gnavus and fecal microbiota from IBS patients with high tryptamine and phenethylamine levels as well as high TyG index." (PMID 37591886, 2023). "However, this hypothesis is contradicted by the effect of some natural TAAR1 agonists, which can elicit insulin resistance." (PMID 38002300, 2023). "Notably, genetic ablation of Taar1 significantly suppressed the expression of Taar1 in metabolic tissues (p < 0.001 in all cases) and protected against tryptamine and phenethylamine-induced glucose intolerance and insulin resistance in mice (p < 0.05 in all cases)." (PMID 37591886, 2023).
mental disorder (3 papers, 2018 to 2023). A disease that has its basis in the disruption of mental process. "The human gene for TAAR1 maps to locus 6q23, within a region associated with major mental disorders." (PMID 31572197, 2019). "Materials and Methods: We screened a cohort of patients with major mental disorders (n = 104) and a group of healthy controls (n = 130) for TAAR1 variants." (PMID 31572197, 2019). "Here, we screened a cohort of patients with major mental disorders for TAAR1 variants, and we analyzed the potential molecular function of the mutated amino acid side chains by using a three-dimensional (3-D) TAAR1 homology model." (PMID 31572197, 2019). "Our findings indicate that TAAR1 variants with deleterious functional effects may contribute to the etiopathology of mental disorders, supporting the potential relevance of this receptor in the physiology of the CNS." (PMID 31572197, 2019). "Taken together, these preclinical findings point to TAAR1 as a promising target of novel pharmacological interventions for mental disorders." (PMID 31572197, 2019). "The circuitry and subcellular expression pattern of TAAR1 in the CNS make it a reasonable candidate that possibly participates in mental disorders." (PMID 29636691, 2018). "Several clinical trials for TAAR1 agonists have been launched for the treatment of mental disorders." (PMID 29636691, 2018). "Furthermore, TAAR1 relevance for mental disorders provides a promising target for novel psychopharmacological interventions aimed at the treatment of these highly disabling disorders." (PMID 31572197, 2019). "In conclusion, our findings suggest that disruptions of TAAR1 activity may represent a vulnerability mechanism for the development of mental disorders." (PMID 31572197, 2019). "Therefore, for the present screening of TAAR1 variants, we recruited patients suffering from any major mental disorders, rather than focusing on a specific diagnostic category." (PMID 31572197, 2019). "What's more, a novel compound with agonist activity at TAAR1 could relieve negative symptoms (e.g., blunted affect and anhedonia) in mental disorders." (PMID 37002793, 2023).
multiple sclerosis (3 papers, 2018 to 2024). A progressive autoimmune disorder affecting the central nervous system resulting in demyelination. "The involvement of TAAR1 in the pathophysiology of multiple sclerosis (MS) has been also investigated." (PMID 38672247, 2024). "In postmortem brain sections, using immunocytochemistry and fluorescence microscopy, the TAAR1 protein was identified in the macrophages/microglia appearing in white matter and at the borders of lesions in multiple sclerosis patients." (PMID 38672247, 2024). "RT-PCR was used to study the expression of TAAR1 mRNA in CD14+ monocytes obtained from the peripheral blood of patients with multiple sclerosis." (PMID 38672247, 2024). "Notably, a recent report highlighted the expression of TAAR1 in macrophages/microglia bordering multiple sclerosis (MS) lesions, supporting TAAR1 as a novel pharmacological target in cells directly implicated in neuroinflammation." (PMID 37511328, 2023).
nicotine addiction (3 papers, 2018 to 2024). "To date, only three studies have evaluated the effects of TAAR1 agonists on nicotine-related behaviors and demonstrated the inhibitory effects of the TAAR1 agonists on nicotine addiction, relapse to nicotine, and nicotine withdrawal." (PMID 38338760, 2024). "Further studies aimed at analyzing the effects of TAAR1 agonists on animal models of nicotine addiction are warranted." (PMID 29681856, 2018).
sleep disorder (3 papers, 2018 to 2021). A change from the patient's baseline sleeping pattern, in the hours slept and/or an alteration/dysfunction in the stages of sleep. "Based on several preclinical studies with selective TAAR1 agonists, and the recent clinical findings with SEP-3638561, TAAR1 has emerged as a promising therapeutic target for mental illness, addiction, and sleep disorders." (PMID 33879769, 2021).
type 2 diabetes (3 papers, 2023 to 2024). "Our in silico analysis demonstrates that TAARs, especially TAAR1, may be involved in the complex regulation of GSIS in the response to chemical stimuli, which is destroyed in type 2 diabetes and prediabetic metabolic disorders." (PMID 38002300, 2023).
Alzheimer disease (2 papers, 2018 to 2025). A progressive, neurodegenerative disease characterized by loss of function and death of nerve cells in several areas of the brain leading to loss of cognitive function such as memory and language. "Trace amines, such as DMT, have the potential to bind with high affinity and activate trace amine-associated receptor 1 (TAAR1) receptors, which may contribute to Alzheimer’s disease (AD) pathology." (PMID 41008295, 2025).
amyloidosis (2 papers, 2023). A disorder characterized by the localized or diffuse accumulation of amyloid protein in various anatomic sites. "Furthermore, we have previously demonstrated that T1AM neuroprotective actions in models of amyloidosis, ischemia–reperfusion injury, and neuroinflammation are dependent on TAAR1." (PMID 37762153, 2023).
HIV-1 infection (2 papers, 2018 to 2024). The type species of lentivirus and the etiologic agent of acquired immunodeficiency syndrome (AIDS). "Overall, current data suggest an association of TAAR1 expression, HIV-1 infection and METH and therefore more study of this possible connection is warranted." (PMID 29997511, 2018). "Following the current model of pseudotyped HIV-1 infection in astrocytes, we confirmed a HIV-1 dose-dependent upregulation in TAAR1 mRNA expression." (PMID 39175523, 2024).
irritable bowel syndrome (2 papers, 2023 to 2026). Irritable bowel syndrome (IBS) is a chronic functional condition of the lower gastrointestinal (GI) tract characterized by abdominal pain or discomfort and disordered bowel habit (diarrhea, constipation, or fluctuation between the two). "Our studies further identified TAAR1 on enterochromaffin cells, where microbial trace amines (Tryp, PEA, and Tyr) activate the receptor to trigger 5-HT release—a mechanism implicated in diarrhea in irritable bowel syndrome (IBS) patients." (PMID 41550498, 2026).
lung carcinoma (2 papers, 2020 to 2021). "In addition, they also reported both a TAAR1-downregulation of in sarcoma, renal, cervical, liver, kidney, pancreas, prostate, pituitary, and uterine cancers, and an upregulated expression of TAAR1 in esophageal, stomach and lung cancers." (PMID 33113952, 2020).
neuroblastoma (2 papers, 2018 to 2026). Neuroblastoma (NB) is the most common solid, extracranial childhood tumor. "Our findings suggest the non-specific activity of trace amines against tumor cells, with a paradoxical stimulatory effect in differentiated neuroblastoma cells, which highlights the need for caution in studies involving TAAR1-specific compounds." (PMID 42278562, 2026).
sarcoma (2 papers, 2018 to 2020). A usually aggressive malignant neoplasm of the soft tissue or bone. "A TAAR1 mRNA transcript query in BioXpress revealed that TAAR1 is upregulated in esophageal, lung, and stomach cancers, and downregulated in sarcoma, cervical, renal, kidney, liver, pancreas, pituitary, prostate, urinary, and uterine cancers." (PMID 29997511, 2018).
stress-related disorder (2 papers, 2025). Stress-related disorders are mental health disorders that are a result of an atypical response to both short and long-term anxiety due to physical, mental, or emotional stress. "Additionally, we attempted to reconstruct gene networks underlying TAAR1-dependent signaling mechanisms, thereby providing novel insights into the molecular framework through which TAAR1 modulation may confer therapeutic benefit in trauma- and stress-related disorders." (PMID 41462983, 2025). "Recent evidence over the past two decades suggests that TAAR1 agonists can influence stress-related behaviors and may serve as potential pharmacotherapeutics for stress-related disorders." (PMID 40351432, 2025).
thyroid cancer (2 papers, 2018 to 2021). "A similar gene-specific query in the Cancer RNA-Seq Nexus revealed that human TAAR1 is statistically differentially expressed in breast, bladder, cervical, lung, pancreatic, stomach, renal, and thyroid cancer." (PMID 29997511, 2018). "It is therefore obvious that the presence of cilia is required to allow trafficking of Taar1 to these appendages of the apical surface of rodent thyrocytes, and that a direct connection between the presence of cilia and thyroid cancer is not reproduced by the human cell line KTC-1 (this study)." (PMID 34208608, 2021).
viral infection (2 papers, 2016 to 2018). "With regard to viral infections, however, our search of NCBI GEO revealed expression array studies in which human PBMC samples were devoid of TAAR1 at baseline." (PMID 29997511, 2018). "The consequences of SNP-induced structural or functional changes in TAAR1 on HIV-1-mediated receptor expression are unknown, but could result in altered cellular response to the viral infection." (PMID 27031617, 2016).
adrenocortical cancers (1 paper, 2018). "It is interesting to note the substantial difference in TAAR1 RNA expression levels between the anatomically closely related adrenocortical cancers and the neuroendocrine cancers pheochromocytoma/paraglioma." (PMID 29997511, 2018).
AIDS (1 paper, 2018). A syndrome resulting from the acquired deficiency of cellular immunity caused by the human immunodeficiency virus (HIV). "It is interesting to note that for TAAR1, expression appears to increase upon initial infection, decrease once the asymptomatic phase is reached, and return to control-baseline levels with progression to AIDS." (PMID 29997511, 2018).
behavioral addiction (1 paper, 2018). "In this regard, more detailed studies are required to unveil the role of TAAR1 in other types of behavioral addiction." (PMID 29636691, 2018). "This study suggests the possibility that TAAR1 could also be involved in the regulation of behavioral addiction in the way that is similar to drug addiction." (PMID 29636691, 2018). "The potential involvement of TAAR1 agonists in behavioral addiction is poorly understood." (PMID 29636691, 2018). "Limited data also suggest that TAAR1 agonists could be useful to treat non-drug related behavioral addiction." (PMID 29636691, 2018).
behavioral disorders (1 paper, 2025). "Unstressed animals treated with LK00764 mirrored these neurochemical patterns, reinforcing the notion that TAAR1 influences both the dopaminergic and serotonergic systems, as recognized in various behavioral disorders." (PMID 41462983, 2025).
bone cancer (1 paper, 2018). A primary or metastatic malignant neoplasm affecting the bone or articular cartilage. "Our meta-analysis revealed that higher expression of TAAR1 correlates to longer median survival time in gastric, ovarian, colorectal, bladder, blood, rectal, and bone cancers." (PMID 29997511, 2018).
brain cancer (1 paper, 2018). A primary or metastatic malignant neoplasm affecting the brain. "Conversely, lower TAAR1 expression correlated to longer median survival in head and neck, skin, and brain cancers." (PMID 29997511, 2018).
cancers of the kidney (1 paper, 2018). "Therefore, TAAR1 RNA is most highly expressed in cancers of the kidney, skin, and neuro-endocrine cancers." (PMID 29997511, 2018).
cardiac arrhythmia (1 paper, 2016). Any disturbances of the normal rhythmic beating of the heart or MYOCARDIAL CONTRACTION. "In the periphery, TAAR1 receptors have been identified in cardiac ventricular tissue, and TAAR1 function has been implicated in cardiac arrhythmias." (PMID 27031617, 2016).
choroid plexus papilloma (1 paper, 2022). "Moreover, TAAR1 also mediates the response to spermidine or cadaverine that has been shown in the choroid plexus papilloma HIBCPP cells." (PMID 35681508, 2022).